PRDM14 (PR/SET domain 14)
Diseases named in the same sentence as PRDM14 in open-access papers (continued):
Sharing a sentence is not in itself a finding about the gene and the disease.
leukemia (5 papers, 2008 to 2020). A malignant (clonal) hematologic disorder, involving hematopoietic stem cells and characterized by the presence of primitive or atypical myeloid or lymphoid cells in the bone marrow and the blood. "Prdm14 misexpression could also promote RAG-dependent driver mutations at loci other than Notch1 in lymphoid cells to cause the other lymphoid-lineage leukemias we previously observed in other PRDM14-induced models." (PMID 27106930, 2016). "We previously demonstrated that Prdm14 is a potent leukemia oncogene, which can cause B-, T- or mixed-lineage lymphoblastic leukemia when expressed in stem-cell-enriched bone marrow via retroviral transduction, albeit with incomplete penetrance and a long latency of 12–52 weeks." (PMID 24046360, 2013). "Such information suggests that Prdm14 may predispose to leukemia development only under certain genetic conditions." (PMID 19043588, 2008). "Using a PRDM14-FLAG mouse model, we show that PRDM14 binds within an intron of Notch1 prior to leukemia development." (PMID 27106930, 2016). "This will allow us to fully dissect the molecular mechanisms of PRDM14-mediated tumor initiation, progression, and relapse in leukemia, as well as in solid tumor models." (PMID 27106930, 2016). "In the PRDM14 leukemia mouse model described here, every animal develops T-ALL and disease progression is extremely rapid." (PMID 24046360, 2013). "We have previously shown that bone-marrow-transduction-derived PRDM14 leukemias are highly aneuploid, harbor numerous copy number alterations (CNAs), and have altered expression of chromosome stability, DNA repair and recombination factors." (PMID 24046360, 2013). "Furthermore, novel findings demonstrated that PRDM14 requires the master hematopoietic regulator CBFA2T3 to initiate leukemia in progenitor cells." (PMID 32290321, 2020). "Here, we show that PRDM14 binds to the Notch1 locus prior to leukemia onset." (PMID 27106930, 2016). "Furthermore, Prdm14 is repressed in normal somatic tissues but is aberrantly reactivated in human malignancies of various tissue origin, including leukemias and lymphomas, breast, testicular, and lung cancers." (PMID 26523391, 2015). "Therefore, we performed ChIP for FLAG in unsorted whole bone marrow (BM), which contains a mixture of FLAG-PRDM14 expressing and non-expressing cells, of R26FLPR;Mx1-cre mice 10 days after induction of Prdm14 expression to determine if PRDM14 binds to this region prior to leukemia development." (PMID 27106930, 2016). "Mice overexpressing PRDM14 in HSCs typically succumb to leukemia by 8-weeks of age, precluding our ability to make this observation previously and making the Rag1−/− genetic background ideal for future studies to fully dissect the function of PRDM14 in hematopoietic progenitor cells." (PMID 27106930, 2016). "Furthermore, PRDM14 bound to a region within the fourth intron of Notch1 prior to leukemia onset, and may have promoted epigenetic changes that enhanced the accessibility of the Notch1 cRSSs to the RAG complex." (PMID 27106930, 2016). "Our research indicates that Prdm14 may also be involved in murine leukemia/lymphoma development." (PMID 19043588, 2008).
lymphoblastic leukemia (5 papers, 2012 to 2020). "PRDM14 has been implicated in a large number of human solid tumors and acute lymphoid leukemias." (PMID 27106930, 2016). "For instance, a mouse lymphoblastic leukemia (LL) with retroviral integration displayed aberrant expression of Prdm14." (PMID 32290321, 2020). "Lastly, aberrant reactivation of the PRDM14 locus is associated with a variety of human cancers, and mice overexpressing Prdm14 in blood cells develop early-onset T-cell acute lymphoblastic leukemia (T-ALL)." (PMID 26523391, 2015). "Not only does this model work efficiently, but lymphoblastic leukemia develops with a very short latency, making this model a robust method for determining the molecular function of PRDM14 and its role in tumorigenesis." (PMID 24046360, 2013). "We have recently identified PR containing domain 14 (Prdm14) as a novel oncogene whose misexpression in hematopoietic precursors leads to B-cell differentiation block and, ultimately, lymphoblastic leukemia and lymphoma." (PMID 23487523, 2012). "Required for reacquisition of pluripotency in the developing germ cell, PRDM14 initiates lymphoblastic leukemia when misexpressed in murine bone marrow." (PMID 23487523, 2012). "Activation of pluripotency in somatic cells can lead to aneuploidy and copy number alterations during iPS cell generation, and we hypothesized that PRDM14-induced lymphoblastic leukemias would demonstrate significant chromosomal damage." (PMID 23487523, 2012).
seminoma (4 papers, 2015 to 2025). A radiosensitive malignant germ cell tumor found in the testis (especially undescended), and extragonadal sites (anterior mediastinum and pineal gland). "From them, EC-, pluripotency- and reprogramming-associated genes REX1 (ZFP42), DND1, JARID2 and PRDM14 were hypomethylated and upregulated, while seminoma-related genes PRDM1, PROM1 and IGF1 became hypermethylated and were downregulated." (PMID 26226633, 2015). "Under in vitro differentiating conditons both, the parental and SOX2-deficient TCam-2 cells downregulated pluripotency/seminoma markers OCT3/4, TFAP2C, PRDM14 and PRAME, while SOX2 and DNMT3B expression remained low." (PMID 27283990, 2016). "PRDM14, which is differentially methylated and expressed between the seminoma and YST cell lines (methylated and silenced in YST), merits special attention." (PMID 29263807, 2016). "Together, these data suggest that PRDM14 could play a central role in GCT progression in which it is initially expressed in seminomas hence helping to retain their germ cell-like phenotype." (PMID 29263807, 2016). "Additionally, many pluripotency and EC associated genes, like SOX2, ZIC3, ZFP42, LIN28, SALL4 and PRDM14 were upregulated without correlating to changes in their 5mC status, while seminoma markers SOX17, cKIT, PRDM1 and PRAME were downregulated." (PMID 27283990, 2016). "Among them, GDF3, NODAL, LEFTY1 /2, GAL, DPPA3, SOX2, DNMT3B /L, DPPA5, BCAT1, FGF2, PRDM14, ZIC3 and FZD7, while seminoma markers SOX17, cKIT and PRAME were downregulated." (PMID 26226633, 2015). "Another study in seminomas indicates that the overexpression of PRAME and its interaction with Lin28A support pluripotency networks and expression of reprogramming markers, such as DPPA3, Nanog, Oct3/4, ZSCAN10, and PRDM14." (PMID 40961095, 2025).
T-cell acute lymphoblastic leukemia (4 papers, 2013 to 2020). Acute lymphoblastic leukemia of T-cell origin. "In addition, in T-cell ALL, PRDM14 binds an intron of Notch1 gene and modifies the chromatin structure by inducing H3K4me3, allowing the access of the RAG recombinase complex." (PMID 32290321, 2020). "In addition, PRDM14 was upregulated in about 25% of human lymphoid neoplasms with increased frequencies in T-cell ALL and hyper-diploid precursor B-cell ALL." (PMID 32290321, 2020). "However, hematopoietic expression of Prdm14 at supraphysiological levels results in fully penetrant and rapid-onset T-cell acute lymphoblastic leukemia (T-ALL) in the mouse." (PMID 27106930, 2016).
bladder cancer (3 papers, 2017 to 2022). "All nine urinary methylation markers (FAM19A4, GHSR, MAL, miR-129, miR-935, PHACTR3, PRDM14, SST and ZIC1) showed significantly higher methylation levels in bladder cancer patients than in controls (p < 0.001)." (PMID 35123558, 2022). "The urinary methylation levels of FAM19A4, GHSR, MAL, miR-129, miR-935, PHACTR3, PRDM14, SST and ZIC1 were significantly higher in patients with bladder cancer than in controls (all, p < 0.001)." (PMID 35123558, 2022). "These encompass seven protein-coding genes (FAM19A4, GHSR, MAL, PHACTR3, PRDM14, SST and ZIC1)—of which, the CpG islands are methylated in bladder cancer—as well as two miRNAs (miR-129 and miR-935) with promoter regions that are also known to be methylated in bladder cancer." (PMID 32252299, 2020).
cervical cancer (3 papers, 2017 to 2019). A primary or metastatic malignant neoplasm involving the cervix. "At the threshold corresponding to 80% specificity in controls, all 6 DNA methylation markers revealed a high sensitivity varying from 76% (FAM19A4 and PHACTR3) to 83% (PRDM14 and ZIC1) for cervical cancer detection in urine sediments." (PMID 30816167, 2019).
germ cell tumor (3 papers, 2013 to 2023). A benign or malignant, gonadal or extragonadal neoplasm that originates from germ cells. "A genome-wide association studies (GWAS) analysis identified nine new susceptibility loci associated with testicular germ cell tumors; these loci comprise genes conceivably related to the development of this cancer, including PRDM14, which is essential for early germ cell specification." (PMID 32290321, 2020). "Alterations of the 8q13.2 region with PRDM14 copy number gain were also found in intracranial germ cell tumors and in head and neck cancer." (PMID 32290321, 2020). "Accordingly, elevated PRDM14 expression was recently detected in all the tested germ cell tumors, a heterogeneous group of tumors occurring in gonadal and extragonadal locations, except for teratomas; in these tumors PRDM14 may act by blocking differentiation." (PMID 32290321, 2020). "Compared to pluripotent human ESCs (HUES9) and a human pluripotent germ cell tumor line (NCCIT) the expression of Oct4 mRNA, Nanog mRNA and Prdm14 mRNA was much lower in BM-MSCs." (PMID 23758701, 2013).
lymphoma (3 papers, 2008 to 2020). A malignant (clonal) proliferation of B- lymphocytes or T- lymphocytes which involves the lymph nodes, bone marrow and/or extranodal sites. "This is probably due to strain specific genetic background differences in strain 27 that predispose mice to Prdm14-induced lymphoid cancer." (PMID 19043588, 2008). "Our research suggests that Prdm14 is a novel proto-oncogene involved in the formation of lymphoma in mice." (PMID 19043588, 2008). "Therefore, we propose that retroviral integration at Evi32 leads to a massive overexpression of Prdm14 contributing to lymphoma in these mice." (PMID 19043588, 2008). "However, for Prdm14, we observed high expression of a PR-domain containing transcript in all Evi32 lymphomas." (PMID 19043588, 2008). "Importantly, it has been shown that PRDM14 overexpression leads to lymphoma formation in mice." (PMID 33287742, 2020).
schizophrenia (3 papers, 2022 to 2024). A major psychotic disorder characterized by abnormalities in the perception or expression of reality. "In the OpenTargets database, alterations in ADNP have been associated with autism spectrum disorders, intellectual disability, dysmorphic features, and hypotonia, JUN with Alzheimer's disease, and PRDM14 with schizophrenia." (PMID 36414996, 2022). "Among the 29 TFs activated in male PD patients, ADNP, JUN, MBD3, PRDM14, and ESR1 have known associations with neurodegenerative disorders such as Alzheimer's disease, mental retardation, schizophrenia, and autism." (PMID 36414996, 2022). "Finally, PRDM14 has key role in modulating specific regulatory functions in schizophrenia, suggesting a possible mechanism for these three TFs to affect these conditions through NDUFV1." (PMID 38632500, 2024).
testicular cancer (3 papers, 2016 to 2022). A primary or metastatic malignant neoplasm that affects the testis. "To address this, we analyzed the correlation between NANOS1 and NANOS3 with its upstream transcriptional program in human primordial germ cells including transcription factors PRDM1, SOX17, TFAP2C, and PRDM14 expression in testis cancer samples." (PMID 36012673, 2022). "PRDM14 mRNA was markedly upregulated in breast, lung, esophagus, pancreas, ovary, kidney, bladder, and testicular cancers compared to expression in the respective normal tissues." (PMID 28423353, 2017).
breast tumor (2 papers, 2016 to 2017). "We observed breast tumor formation in both Prdm14-KO; Wnt-1 and Prdm14flox/flox; Wnt-1 transgenic mice after parturition and lactation." (PMID 28423353, 2017). "Furthermore, an inverse correlation between PRDM14 expression and lymphocyte infiltration into breast tumors indicates that PRDM14-expressing cancer cells escape immunosurveillance." (PMID 28423353, 2017). "Therefore, we speculate that PRDM14 may prevent the detection of breast tumor cells by the immune system to worsen cancer prognosis." (PMID 28423353, 2017). "Furthermore, the expression of OCT4, but not PRDM14, SOX2, REX1 or NANOG was higher in breast tumor and metastasis samples, suggesting negative regulation of Xist by OCT4." (PMID 27248326, 2016).
colorectal cancer (2 papers, 2020 to 2022). A primary or metastatic malignant neoplasm that affects the colon or rectum. "Studies have also shown that PRDM14 has several hypermethylated CpG sites in African-American colorectal cancer patients by using RRBS." (PMID 35065650, 2022). "In addition, these hypermethylated genes, mainly PRDM14, RALYL, ELMOD1, and TMEM132E, were validated and confirmed in colorectal cancer by using publicly available DNA methylation data." (PMID 35065650, 2022). "MeDIP-seq can be used as an optimal approach for analyzing cfDNA methylomes, and 12 probes of four differentially methylated genes identified by MeDIP-seq (PRDM14, RALYL, ELMOD1, and TMEM132E) could serve as potential biomarkers for clinical application in patients with colorectal cancer." (PMID 35065650, 2022).
embryonal carcinoma (2 papers, 2008 to 2021). A non-seminomatous malignant germ cell tumor characterized by the presence of large germ cells with abundant cytoplasm resembling epithelial cells, geographic necrosis, high mitotic activity, and pseudoglandular and pseudopapillary structures formation. "PRDM14 is highly expressed in embryonal carcinoma cell lines, embryonal carcinomas, seminomas, intracranial germinomas, and yolk sac tumors, but is not expressed in teratomas and its overexpression causes proliferation and differentiation defects in hPGCLCs." (PMID 34205983, 2021).
lymphoblastic lymphoma (2 papers, 2008 to 2022). A lymphoma composed of immature small to medium-sized precursor lymphoid cells (lymphoblasts). "This study implicates Prdm14 as a proto-oncogene involved in lymphoblastic lymphoma formation." (PMID 19043588, 2008).
acute pancreatitis (1 paper, 2018). An acute inflammatory process that leads to necrosis of the pancreatic parenchyma. "We prepared both chronic and acute pancreatitis to assess whether continuous inflammation is needed for increased PRDM14 expression." (PMID 30338223, 2018). "On the other hand, acute pancreatitis did not increase PRDM14 expression in normal pancreatic tissue indicating the important effect of chronic inflammation on cancer initiation and tumorigenesis." (PMID 30338223, 2018). "On IHC analysis, PRDM14‐positive cells were observed in chronic pancreatitis models, but not in acute pancreatitis models and controls." (PMID 30338223, 2018). "We induced pancreatitis in mouse models by cerulein injection, and observed that PRDM14 expression increased in chronic pancreatitis models but not in control or acute pancreatitis mice." (PMID 30338223, 2018).
adenoma (1 paper, 2016). A neoplasm arising from the epithelium. "We identified hypermethylated CpG sites in the following genes: L3MBTL1, NKX6-2, PREX1, TRAF7, PRDM14, and NEFM with the number of CpG sites being 14, 17, 10, 16, 6, and 6, respectively, after pairwise analysis of normal versus adenoma, adenoma versus cancer, and normal versus cancer." (PMID 27688749, 2016).
chronic pancreatitis (1 paper, 2018). A chronic inflammatory process causing damage and fibrosis of the pancreatic parenchyma. "Through immunohistochemistry analyses of clinical tissues, we detected PRDM14‐positive cells in precursor pancreatic intraepithelial neoplasia and chronic pancreatitis, which is a risk factor for PDAC, lesions." (PMID 30338223, 2018). "PRDM14 was overexpressed in chronic pancreatitis tissues as well as PDAC and cancer adjacent tissues." (PMID 30338223, 2018). "To estimate the relationship between PRDM14 overexpression and inflammation, we performed experiments using a cerulein‐induced chronic pancreatitis mouse model." (PMID 30338223, 2018). "Our results revealed that cerulein‐induced chronic pancreatitis increased PRDM14 expression in normal mice." (PMID 30338223, 2018). "In this study, we assessed the expression levels of PRDM14 in several pathological tissues, including PanIN and chronic pancreatitis." (PMID 30338223, 2018). "Interestingly, the staining score for PRDM14 in chronic pancreatitis was as elevated as that observed in PDAC and cancer adjacent tissues." (PMID 30338223, 2018). "Therefore, in this report we assessed PRDM14 expression in precursor lesions of PDAC and chronic pancreatitis, which is a risk factor of the disease." (PMID 30338223, 2018). "Taken together, PRDM14 overexpression may be triggered by chronic pancreatitis prior to PDAC and regulate tumor initiation and progression." (PMID 30338223, 2018). "In this study, we detected PRDM14‐positive cells in PanIN and chronic pancreatitis." (PMID 30338223, 2018). "PRDM14‐positive cells were detected in chronic pancreatitis tissues overall." (PMID 30338223, 2018). "Moreover, chronic pancreatitis induced by cerulein increased PRDM14 expression in the pancreases of normal mice." (PMID 30338223, 2018). "PRDM14‐positive cells were observed in both PanIN and chronic pancreatitis." (PMID 30338223, 2018). "PRDM14 staining in chronic pancreatitis was as high as that in PDAC and cancer adjacent tissues." (PMID 30338223, 2018). "Moreover, the staining score for PRDM14 was as high in chronic pancreatitis as in PDAC." (PMID 30338223, 2018). "Therefore, we investigated the relationship between PRDM14 expression and chronic pancreatitis." (PMID 30338223, 2018).
male breast carcinoma (1 paper, 2012). A malignant neoplasm involving the male breast. "Among the other genes studied, copy number gain of MED1, PRDM14, and BIRC5 were associated with a high grade phenotype, indicating that these genes play a role in the development or progression of aggressive male breast cancer." (PMID 22527098, 2012). "Also MED1, PRDM14, MTDH, and BIRC5 seem to be important in the development or progression of high grade male breast cancer." (PMID 22527098, 2012).
melanoma (1 paper, 2020). A malignant, usually aggressive tumor composed of atypical, neoplastic melanocytes. "To confirm the localization of PRDM14 at perimeter features of micropatterned melanoma aggregates, we performed immunofluorescence characterization in both B16 cells and human primary melanoma cells." (PMID 32620903, 2020). "To explore how PRDM14 plays a supportive role in coordinating the epigenetic state of melanoma in response to perimeter geometry, we performed knockdowns of PRDM14 using siRNA." (PMID 32620903, 2020). "siRNA knockdown of PRDM14 abolishes the MIC phenotype suggesting a role in regulating melanoma heterogeneity." (PMID 32620903, 2020). "Human melanoma cells show significant enhancement in both CD271 and PRDM14, suggesting this mechanism is not unique to mouse cell lines but may play a role in guiding the MIC phenotype in human cells." (PMID 32620903, 2020).
metabolic syndrome (1 paper, 2023). A cluster of metabolic risk factors for CARDIOVASCULAR DISEASES and TYPE 2 DIABETES MELLITUS. "PIK3R2, STRA8, FLT1, DMRT1, FGF22, NR5A2, and FLT were up-regulated and PRDM14, POU5F1, and KDR were down-regulated in metabolic syndrome after exercise." (PMID 37053002, 2023).
non-small cell lung carcinoma (1 paper, 2024). A group of at least three distinct histological types of lung cancer, including non-small cell squamous cell carcinoma, adenocarcinoma, and large cell carcinoma. "PRDM14 has carcinogenic potential in breast and non-small cell lung cancer." (PMID 38840106, 2024).